CCL28 (C-C motif chemokine ligand 28)
Diseases named in the same sentence as CCL28 in open-access papers (continued):
Sharing a sentence is not in itself a finding about the gene and the disease.
autoimmune disease (5 papers, 2020 to 2026). A disorder resulting from loss of function or tissue destruction of an organ or multiple organs, arising from humoral or cellular immune responses of the individual to their own tissue constituents. "Pre-surgical level of CCL28 was affected by the history of stroke, peripheral vascular disease, and pre-existing mixed tissue autoimmune disease." (PMID 36271425, 2022). "CCL28 is constitutively expressed by epithelial cells in the colon; it shows strong antimicrobial ability and can recruit Tregs in autoimmune diseases." (PMID 33833986, 2021). "Considering that tumour sites impose distinct chemokine (e.g., CCL22, CCL28) and nutrient constraints compared with inflamed autoimmune tissues, integrating these contexts could broaden the translational relevance of our model to both malignancy progression and autoimmune disease." (PMID 40960283, 2026). "While CCL28 is responsible for the recruitment of various immune cells (which express CCR10 and CCR3) for mucosal tissue and inflammatory sites, some data indicate that it is responsible for recruiting Treg, maintaining tolerance of self antigens and preventing autoimmune diseases." (PMID 33139632, 2020).
lung adenocarcinoma (5 papers, 2016 to 2025). A carcinoma that arises from the lung and is characterized by the presence of malignant glandular epithelial cells. "We then used a public integrative database (cBioPortal) to analyze the correlation of the expression of CEBPB with that of CCL28 in 44 lung adenocarcinoma cell lines." (PMID 39075504, 2024). "The current study delves into the previously undisclosed connection between pericytes and CCL28 in lung adenocarcinoma." (PMID 39075504, 2024). "To clarify the exact role and potential mechanism of CCL28 in vascular normalization, we mimicked the hypoxic microenvironment in lung adenocarcinoma, cultured vascular pericytes, and conducted secretome analysis after CCL28 treatment." (PMID 39075504, 2024). "Our previous report highlighted that CCL28 can moderately enhance the angiogenesis in lung adenocarcinoma." (PMID 39075504, 2024). "The correlation analysis exhibited a positive relationship between RDH13 and CCL28 in lung adenocarcinoma." (PMID 39075504, 2024). "To investigate the effects of CCL28 on tumor growth and vascular normalization, we established CCL28 overexpression and knock-out lung adenocarcinoma cells by lentivirus vectors and Cas9 nuclease/sgRNA, respectively." (PMID 39075504, 2024). "CCL28 was mainly expressed in lung adenocarcinoma cells due to the fluorescence overlapping between CCL28 and PAN-CK." (PMID 39075504, 2024). "In this study, we identified CCL28 as another crucial molecular target for vascular normalization in lung adenocarcinoma." (PMID 39075504, 2024). "We previously reported that high expression of CCL28 was induced in hypoxic lung adenocarcinoma cell lines, A549 and SPC-A1." (PMID 39075504, 2024). "Overexpression and knockout of CCL28 in human lung adenocarcinoma cell line A549 and murine lung adenocarcinoma cell line LLC, respectively, were utilized to establish mouse models." (PMID 39075504, 2024). "Of all chemokines, only CCL28 was simultaneously up-regulated in lung adenocarcinoma cell lines and tumor samples." (PMID 27250766, 2016). "As confirmed in tumor tissue and serum of patients, CC chemokine 28 (CCL28) was the only hypoxia induced chemokine in lung adenocarcinoma cells." (PMID 27250766, 2016). "In conclusion, CCL28, one of the CC chemokines, is identified as another hypoxia induced molecule in lung adenocarcinoma." (PMID 27250766, 2016). "Tumors formed by lung adenocarcinoma cells with high expression of CCL28 grew faster and had a higher vascular density, whereas tumor formation rate of lung adenocarcinoma cells with CCL28 expression knockdown was quite low and had a lower vascular density." (PMID 27250766, 2016). "As VEGFA is one of the hypoxia induced genes, the concentration of VEGFA in the serum of lung adenocarcinoma patients was examined by ELISA (22 in 27 blood samples for the study of serum concentration of CCL28)." (PMID 27250766, 2016). "Taken together, at least two major roles are played by CCL28 in lung adenocarcinoma, including immunosuppression and pro-angiogenesis (directly and indirectly), both of which are important targets for cancer therapy." (PMID 27250766, 2016). "CCR3, receptor of CCL28, was highly expressed in vascular endothelial cells in lung adenocarcinoma when examining by immunohistochemistry." (PMID 27250766, 2016). "Subsequently, CCL28 expression was also examined by RT-PCR in lung adenocarcinoma tumor tissues cultured under hypoxic condition (n = 4)." (PMID 27250766, 2016). "Our study showed that after undergoing anti-angiogenesis treatment, the tumor exhibited a state of ischemia and hypoxia, leading to an upregulation in the expression of CCL28 in hypoxic lung adenocarcinoma cells by the hypoxia-sensitive transcription factor CEBPB." (PMID 39075504, 2024).
lung adenocarcinoma (continued). "The findings revealed a significant increase in the hypoxia index (GLUT1, one of the primary target genes regulated by hypoxia-inducing factor HIF-1) and up-regulation of CCL28 expression in lung adenocarcinoma patients 24 h after VEGF monoclonal antibody treatment compared to baseline levels." (PMID 39075504, 2024). "As we previously reported, in vivo studies indicated that CCL28 could promote tumor growth in A549 human lung adenocarcinoma." (PMID 39075504, 2024). "Subcutaneously implanted lung adenocarcinoma cells with CCL28 knock-out grew much slower than wild-type tumor cells, while combination of VEGF blocker could stop the growth of the tumors." (PMID 39075504, 2024). "In conclusion, hypoxia of lung adenocarcinoma cells could induce both tumor immunosuppression and angiogenesis through the up-regulation of CCL28." (PMID 27250766, 2016). "As a result, CCL28 might be an ideal target to both inhibit tumor immunosuppression and angiogenesis in lung adenocarcinoma." (PMID 27250766, 2016). "Serum concentration of CCL28 of lung adenocarcinoma patients was further studied." (PMID 27250766, 2016). "As a result, CCL28 could promote angiogenesis in lung adenocarcinoma and bypass the effects of VEGFA." (PMID 27250766, 2016). "In conclusion, CCL28, as a chemokine induced by tumor hypoxia, could promote angiogenesis in lung adenocarcinoma through targeting CCR3 on microvascular endothelial cells." (PMID 27250766, 2016). "Interestingly, CCL28 expression was also much higher in the blood serum of lung adenocarcinoma patients, compared to that in the serum of healthy donors (5009.10 ± 504.76ng/ml vs. 902.27 ± 221.50 ng/ml, p < 0.001)." (PMID 27250766, 2016). "Also, the expression level of CCL28 in lung adenocarcinoma correlates with therapeutic efficacy." (PMID 39075504, 2024). "Therefore, we hypothesized that CCL28 might play a pivotal role in modulating the tumor microenvironment in lung adenocarcinoma." (PMID 39075504, 2024). "However, in the present study, the expression of CCR3 was identified in the microvascular endothelial cells of lung adenocarcinoma, which could be directly affected by CCL28." (PMID 27250766, 2016). "Besides other effects on tumor biology, such as immunosuppression, CCL28 could promote angiogenesis in lung adenocarcinoma by directly activating its receptor, CCR3, on microvascular endothelial cells." (PMID 27250766, 2016). "Lung adenocarcinoma cell lines, A549 and SPC-A1, with stable over expression of CCL28 were screened out and implanted subcutaneously in BALB/c nude mice." (PMID 27250766, 2016). "Moreover, we investigated the synergistic effects of CCL28 knock-out and VEGF blocking on the tumor growth and vascular normalization of lung adenocarcinoma." (PMID 39075504, 2024). "Taken together, the evidences indicated that CCR3, but not CCR10, was the main receptor of CCL28 on the microvascular endothelial cells, especially in lung adenocarcinoma." (PMID 27250766, 2016). "Furthermore, CCL28 has been identified as a potential biomarker for predicting immunotherapy responses in lung adenocarcinoma, particularly in patients non-responsive to treatment." (PMID 40508156, 2025). "CCL28 was up-regulated in all three lung adenocarcinoma cell lines, whereas others were not." (PMID 39075504, 2024). "While one study discovered that CCL28 increased the proliferation, migration, and secretion of IL-6 and HGF in oral fibroblasts, the functional role of CCL28 in pericytes in lung adenocarcinoma has not been elucidated." (PMID 39075504, 2024).
melanoma (5 papers, 2014 to 2025). A malignant, usually aggressive tumor composed of atypical, neoplastic melanocytes. "CCL28/MEC expression is increased in response to cycling hypoxia in the WM793B melanoma cell line." (PMID 32781743, 2020). "Thus, CCR10 and CXCL12/CXCR4 may regulate homing of CD4+ Tregs to B16 melanoma tumors while invasion of NBL tumors by CD4+ Tregs is likely governed by CCL28/CCR10 and CXCL12." (PMID 34721405, 2021).
Obesity (5 papers, 2013 to 2023). Accumulation of substantial excess body fat. "Methods & Results: Firstly, a higher level of CCL28 was observed in skin and plasma in both patients with T2DM, and in obesity-induced type 2 diabetic db/db mice." (PMID 36713846, 2023). "Here we demonstrate that neutralization of excessive CCL28 not only reduced inflammation but also CCR10-eNOS interaction in diabetic wounds, thereby enhancing eNOS/NO level, VEGF production, microvessel density, and wound healing in the obesity-induced mouse model of type 2 diabetes." (PMID 36713846, 2023).
colitis (4 papers, 2012 to 2024). Inflammation of the colon. "Strikingly, we observed increased neutrophil abundance in the intestinal tissues of wild-type mice during colitis, but ~50% fewer neutrophils (CD11b+ Ly6G+ cells) were isolated from the gut of Ccl28−/− mice 2 and 3 days after STm infection." (PMID 39193987, 2024). "We investigated CCL28 activity during gastrointestinal infection with STm by using the well-established streptomycin-treated C57BL/6 mouse model of colitis." (PMID 39193987, 2024). "Based on these findings and our observations of CCL28-dependent neutrophil accumulation in the gut during STm colitis and in the lung during Ab infection, we performed flow cytometry on single-cell suspensions from infected mouse tissues to evaluate surface expression of CCR3 and CCR10." (PMID 39193987, 2024). "Thus, CCL28 modulates neutrophil accumulation and drives inflammatory tissue pathology and colitis during STm infection." (PMID 39193987, 2024). "In the mouse gut, CCL28 production is increased in the dextran sulfate sodium model of colitis." (PMID 39193987, 2024). "Interestingly, the expression of a set of genes encoding chemokines involved in homeostatic processes, including CCL21, CCL25, CCL27 and CCL28, was gradually down-regulated in our TNBS colitis model." (PMID 23226271, 2012).
colon cancer (4 papers, 2023 to 2024). "Of note, Ccl28, encoding CCL28, a major chemokine involved in Treg cell trafficking, showed a marked induction in colon tumor tissues from BF BSHhigh-colonized mice." (PMID 36765047, 2023). "Bile acids promoted WNT signaling and upregulated CCL28 expression in a β-catenin-dependent manner in colon tumor tissues." (PMID 36765047, 2023). "In this study, CCL28 gene expression was more active in M0 patients compared to colon cancer with distant metastases." (PMID 36890467, 2023). "In this work, NTBF is found to potentiate CRC progression depending on the high activity of BSH, activation of the β-catenin-CCL28 axis and induction of Treg cells infiltration in colon tumors." (PMID 36765047, 2023). "RNA-seq analysis revealed that microbial BSH overexpression enhanced the relative expression of Ccl28 in colon tumor tissue, suggesting a role for BSH in regulating the intra-tumoral immune response." (PMID 36765047, 2023). "Elevated expression of EMS1 and the chemokine CCL28 produced by intestinal mucosal epithelial cells were common in colon cancer patients." (PMID 36890467, 2023). "In the presence of high BSH activity, the resultant elevation of unconjugated deoxycholic acid and lithocholic acid activates the G-protein-coupled bile acid receptor, resulting in increased β-catenin-regulated chemokine (C-C motif) ligand 28 (CCL28) expression in colon tumors." (PMID 36765047, 2023). "In addition, expression levels of IGKV1-6, IGLV6-57, and CCL28 were higher in colon cancer, while VIP and FABP4 were more biased to be expressed in high-risk group." (PMID 36890467, 2023). "Either CCL28 or CD25 blockade decreased Treg cell accumulation, resulting in the increase of cytotoxic CD8+ T cells in colon tumor tissues." (PMID 36765047, 2023). "Either degradation of β-catenin or absence of TGR5 decreased the relative expression of Ccl28 in colon tumor organoids." (PMID 36765047, 2023). "In vitro, C7 treatment had no direct effect on the β-catenin/CCL28 axis in cultured colon tumor-derived organoids." (PMID 36765047, 2023).
COVID-19 (4 papers, 2021 to 2024). A disease caused by infection with severe acute respiratory syndrome coronavirus 2. "In contrast, CCL22, CCL28, and Fms-related tyrosine kinase 3 ligand (Flt3L) were positively correlated with basophil frequency, particularly in COVID-19 patients with moderate disease." (PMID 34548411, 2021). "Moreover, we identified several other inflammation-related proteins that are linked to COVID-19, such as CD209, CD58, CCL15, CCL28, and MNDA." (PMID 38575325, 2024).
liver cancer (4 papers, 2016 to 2024). An epithelial or non-epithelial malignant neoplasm that arises from the liver. "Given the similar mechanism of CCL28 in promoting ovarian and liver cancer development, it is necessary to distinguish the different molecular details mediated by CCL28 functions in different systems." (PMID 27716621, 2016). "In line with previous reports, our study confirms that hypoxia directly induces the upregulation of CCL28 in liver cancer." (PMID 27716621, 2016). "It is worth noting that the CCL20-CCR6 axis, CCL1-CCR8 axis, and CCL28-CCR axis can all induce the proliferation and migration of liver cancer cells, recruit immunosuppressive cells TAM and Tregs, and promote immune tumor escape." (PMID 38069309, 2023).
pancreatic cancer (4 papers, 2023 to 2024). "In pancreatic cancer, in vitro CCL28 knockdown suppressed intrinsic PDAC cell proliferation, while CCL28 downregulation in vivo promoted the extrinsic upregulation of cytotoxic proteins, including perforin and the decreased infiltration of pancreatic stellate cells (PSCs) and blood vessel formation." (PMID 36841432, 2023). "Taken together, our findings suggested that CCL28 might represent a promising therapeutic target for pancreatic cancer." (PMID 37380804, 2023). "Mechanistically, we found that FOSL2 bound to the upstream region of CCL28 to activate its expression, leading to the recruitment of Treg cells and highlighting the importance of the FOSL2-CCL28-Treg axis in pancreatic cancer." (PMID 37380804, 2023). "In the present study, we identified CCL28 as a key mediator linking FOSL2 and the pancreatic tumour microenvironment." (PMID 37380804, 2023). "By blocking CCL28 expression upon FOSL2 overexpression, we successfully suppressed Treg cell infiltration and tumour growth, providing insights into the role of FOSL2 in shaping the immune microenvironment of pancreatic cancer." (PMID 37380804, 2023). "Importantly, our study demonstrated that CCL28 blockade upon FOSL2 overexpression exerted a potent anti-tumour effect by suppressing Treg cell infiltration and might serve as a potential therapeutic target for pancreatic cancer." (PMID 37380804, 2023).
viral infection (4 papers, 2011 to 2021). "Crosslinking FcεRI drives production of CCL28, which is required for development of post‐viral disease." (PMID 28474501, 2017). "We thereby suggest that a study of the role of a CCR10 antagonist such as POL7085 in the CCL28-driven lung T cell recruitment during viral infections in mice would be useful." (PMID 26112287, 2015). "Notably, the usefulness of CCL28 as an adjuvant for mucosal vaccination was confirmed by recent data showing that the association of CCL28 and a DNA-based vaccine results in the generation of a potent immune response that prevents mucosally transmitted viral infections." (PMID 22066023, 2011). "Therefore, we hypothesized that treatment with anti‐CCL28 or POL7085 would alter the cytokines being produced during the viral infection." (PMID 28474501, 2017).
malaria (3 papers, 2022 to 2025). Malaria is a serious and sometimes fatal disease caused by a parasite that commonly infects a certain type of mosquito which feeds on humans. "Low levels of CCL28 were detected in individuals with malaria symptoms, which is a chemokine involved in regulating angiogenesis and nitric oxide." (PMID 37048057, 2023). "They demonstrated that malaria and L. loa co-infections had decreased levels of C-X-C motif chemokine 5 (CXCL5) and comparable levels of CX3CL1, CXCL7, CXCL9, CXCL11, and CCL28 compared with malaria monoinfection." (PMID 36269701, 2022).
pancreatic ductal adenocarcinoma (3 papers, 2023 to 2025). An infiltrating adenocarcinoma that arises from the epithelial cells of the pancreas. "In pancreatic ductal adenocarcinoma (PDAC), CCL28 is upregulated, with a negative correlation with overall survival (OS)." (PMID 40508156, 2025).
periodontitis (3 papers, 2017 to 2025). An acute or chronic inflammatory process that affects the tissues that surround and support the teeth. "Co-expression analysis revealed enrichment in immune and oral health-associated pathways, including salivary protein's role in periodontitis (p=0.007; OR=118.8; LYZ, LTF) and dental caries (p=0.007; OR=59.36; LYZ, CCL28)." (PMID 41552085, 2025). "Among them, complement components C6, C8A, and C8B, as well as chemokine ligand 28 (CCL28), were highlighted in the periodontitis group." (PMID 41322905, 2025). "Salivary exosomal cargo in periodontitis includes complement components C6, C8A, C8B, and chemokine CCL28, together with decreased CD9/CD81 and elevated PD-L1 mRNA, which may indicate altered immune regulation and correlate with disease severity." (PMID 41322905, 2025). "Other strongly associated proteins in this pathway were salivary proteins involved in periodontitis (OR=118.80, adjusted, p=0.007; genes: LYZ, LTF) and proteins involved in dental caries (OR=59.36, p=0.007; genes: LYZ, CCL28)." (PMID 41552085, 2025). "Among these pathways, key pathways relevant to our hypothesis include the role of salivary proteins in periodontitis (OR=118.80, adjusted, p=0.007; genes: LYZ, LTF) and proteins involved in dental caries (OR=59.36, p=0.007; genes: LYZ, CCL28)." (PMID 41552085, 2025).
rheumatoid arthritis (3 papers, 2022 to 2024). A chronic, systemic autoimmune disorder characterized by inflammation in the synovial membranes and articular surfaces. "Similar to these findings, we previously reported that overexpression of CCL28/CCR10 in synovial tissue was associated with upregulation of angiogenesis in patients with rheumatoid arthritis." (PMID 36713846, 2023). "CCL28 has been linked to the recruitment of Treg cells, however CCL28 and its receptor CCR10 were also proposed to be pathogenic in rheumatoid arthritis." (PMID 35967338, 2022). "We previously observed protein expression of CCL28 and CCR10 to be upregulated by LPS and pro-inflammatory cytokines such as TNF-α and IL-6 in monocytes and macrophages isolated from patients with rheumatoid arthritis (RA)." (PMID 36713846, 2023).